BDNF (brain derived neurotrophic factor)
Diseases named in the same sentence as BDNF in open-access papers (continued):
Sharing a sentence is not in itself a finding about the gene and the disease.
bipolar disorder (continued). "Furthermore, we hypothesised that first-degree relatives of patients with bipolar disorder would express intermediary BDNF levels." (PMID 33588978, 2021). "After treatment, the concentration of BDNF in the peripheral blood of patients with bipolar disorder was found to be significantly higher than that of healthy people, while the concentration of BDNF in the serum of patients with bipolar disorder was in remission." (PMID 35194435, 2021). "Episodic nature of bipolar disorder may be especially detrimental to maintaining systemic homeostasis, with a repeated need for adaptation and re-setting of parameters, which may lead to high levels of oxidative stress, and decreased BDNF levels." (PMID 33061913, 2020). "At that time, studies focusing on the pathophysiology of bipolar disorder reported a deregulation of oxidative and inflammatory pathways in bipolar disorder, especially during mood episodes, which came with a decrease in neurotrophic factors, like brain-derived neurotrophic factor (BDNF)." (PMID 30555363, 2018). "Thus, increased serum BDNF levels were found in schizophrenic patients that had been chronically medicated with clozapine or other typical and a typical antipsychotics in comparison to healthy controls or to euthymic bipolar disorder patients." (PMID 22654714, 2011). "Core molecular processes involving BDNF-NMDA receptor availability and the resulting neural changes in signal variability are affected in unipolar and bipolar depression." (PMID 38500272, 2024). "Meanwhile, the reductions of plasma levels of BDNF and NGF have been shown in bipolar disorder, and manic and depressed patients." (PMID 38473763, 2024). "Meanwhile, the reduction of plasma levels of BDNF and NGF has been shown in bipolar disorder and manic and depressed patients." (PMID 38473763, 2024). "First, brain-derived neurotrophic factor (BDNF) excitatory neurons were highly enriched in MDD (and several other diseases/traits, including bipolar disorder and SCZ)." (PMID 38233398, 2024). "The NGF, FGF2, NT-3, BDNF, IL-1-β, and dopamine factors also indirectly impact the action of GSK-3β in bipolar disorder." (PMID 37569304, 2023). "Therefore, our findings did not support our hypotheses that patients who have been newly diagnosed with bipolar disorder would have lower BDNF levels compared with healthy controls and that first-degree relatives of patients with bipolar disorder would express intermediary BDNF levels." (PMID 33588978, 2021). "For example, brain derived neurotrophic factor, B-cell lymphoma 2 (bcl-2), and vascular endothelial growth factor (VEGF) are decreased during acute phases of bipolar disorder (both mania and depression)." (PMID 30918489, 2019). "BDNF was found to be decreased in both mania (SMD −1.16, 95% CI −1.5 to −0.81, P < 0.00001, I2 = 32%, k = 4, n = 252) and bipolar depression (SMD −1.35, 95% CI −2.11 to −0.6, P = 0.0004, I2 = 69%, k = 3, n = 251)." (PMID 30113291, 2018). "Biomarker meta-analyses suggest a combination of high-sensitivity C-reactive protein/interleukin-6, brain derived neurotrophic factor/tumour necrosis factor (TNF)-α and soluble TNF-α receptor 1 can differentiate specific mood phase in bipolar disorder." (PMID 30113291, 2018). "The brain-derived neurotrophic factor (BDNF) has been investigated in several neuropsychiatric disorders including MDD, bipolar disorder, and addiction." (PMID 26935651, 2016). "One example is a study that reported a significant interaction effect between BDNF Val66Met and DRD3 Ser9Gly genotypes, influencing bipolar disorder." (PMID 26091093, 2015). "The authors found that serum MDNF, proBDNF, the ratio of BDNF/proBDNF, and interaction with MMP-9 were different between patients with bipolar disorders and healthy controls." (PMID 25089150, 2014). "Given these associations, it is plausible that variations in the serum levels of BDNF and CRP may correspond to differences in cognitive profiles among individuals with bipolar disorder." (PMID 41367212, 2025).
bipolar disorder (continued). "For example, CREB-induced neurotrophic factors like BDNF require regulated expression upon HIT as it is linked with negative effects on brain health, such as inducing bipolar disorder." (PMID 39902166, 2024). "A review also verified lower BDNF both in MDD and bipolar disorder." (PMID 37533888, 2023). "Fourth, we found only weak evidence for a potential causal relationship between immunological proteins/traits with bipolar disorder, limited to BDNF, although the evidence did not meet the conventional or Bonferroni-corrected evidential thresholds." (PMID 34280516, 2021). "BDNF levels have not previously been investigated in newly diagnosed patients with bipolar disorder." (PMID 33588978, 2021). "In contrast, differences in BDNF levels among euthymic bipolar disorder patients vs controls were not significant and of modest magnitude (ES –0.20)." (PMID 32356562, 2020). "Most significantly, a combination of hsCRP/IL-6, BDNF/TNF-α and sTNFR1 may offer the potential to differentiate people with bipolar disorder from matched controls specific to bipolar mood phase." (PMID 30113291, 2018). "As compared to non-Met, BDNF 66Met carriers with bipolar disorder showed a greater increase in triglycerides and triglycerides/HDL-C ratio after three or six months of antipsychotic therapy." (PMID 28056856, 2017). "In the study of D’Addario, a 7 % increase of DNA methylation at the region of BDNF promoter I was observed in bipolar disorder (BD) II patients, but not BD I, compared with controls." (PMID 27267954, 2016). "Furthermore, a meta-analysis showed that brain-derived neurotrophic factor (BDNF) levels were decreased in bipolar mania and bipolar depression when compared with both control groups." (PMID 24971450, 2014). "Another study assessed serum BDNF levels in patients with bipolar disorder and compared those with and without trauma exposure." (PMID 23908608, 2013). "For example, increasing BDNF concentration through exercise can be beneficial for brain health, but it may also have a negative impact on conditions such as bipolar disorder." (PMID 39194500, 2024). "We identified preliminary evidence that peripheral growth factor proteins – the BDNF, the bFGF and VEGF – may moderate the effect of cognitive remediation in those with bipolar disorders, and potentially represent a mechanism for the effect of treatment on functioning." (PMID 39635758, 2024). "In patients with bipolar affective disorder, a negative correlation was found between plasma BDNF and lipid peroxidation product levels, which may indicate that BDNF protects neurons from damage resulting from OS." (PMID 36979300, 2023). "In contrast, we found significantly higher BDNF levels in patients with bipolar disorder compared with healthy controls that could not be explained by alcohol consumption, smoking status or subsyndromal symptoms." (PMID 33588978, 2021). "We hypothesised that patients newly diagnosed with bipolar disorder would have lower BDNF levels compared with healthy controls without a family history of bipolar disorder." (PMID 33588978, 2021). "Exercise also appears to increase brain‐derived neurotropic factor (BDNF) levels in women but not men with bipolar disorder, leading some to hypothesize that exercise promotes neurogenesis." (PMID 32356562, 2020). "The result is interesting in the context of the data provided by Hsu and co-workers, who have shown that bipolar disorder patients develop liver disease more often, while Yang and colleagues found a negative correlation between mature BDNF in the brain and liver of depressed patients." (PMID 32283635, 2020). "Studies on biological markers have also suggested that peripheral concentrations of BDNF could be used to discriminate unipolar depression from bipolar depression, but evidence is not clear." (PMID 30555363, 2018).
bipolar disorder (continued). "More recently, two published meta-analysis suggested decreased levels of peripheral BDNF in bipolar depression but not in mania; however, one had very strict inclusion criteria, and did find BDNF levels decreased in mania after the exclusion of one study which was an outlier." (PMID 26621529, 2015). "Despite the lack of replication observed in our data, BDNF may continue to be an interesting candidate gene for pediatric bipolar disorder." (PMID 19193231, 2009). "This could reduce the negative effect of the BDNF on bipolar disorder." (PMID 39194500, 2024). "Brain-derived neurotrophic factor (BDNF), which facilitates neuroplasticity and synaptogenesis, may be decreased in bipolar disorder, but has not been systematically investigated in people with newly diagnosed bipolar disorder and unaffected first-degree relatives." (PMID 33588978, 2021). "However, higher expression of BDNF might play a negative role in bipolar disorder." (PMID 39239097, 2024).
Huntington disease (223 papers, 2006 to 2026). Huntington disease (HD) is a rare neurodegenerative disorder of the central nervous system characterized by unwanted choreatic movements, behavioral and psychiatric disturbances and dementia. "HTT-AS, ABHD11-AS1, HAR1, TUNA, and brain-derived neurotrophic factor (BDNF)-AS have been implicated in Huntington’s disease." (PMID 39920595, 2025). "This article highlights recent molecular evidence and BDNF signaling pathways implicated in Huntington's disease pathogenesis, as well as the therapeutic potential of experimentally modifying BDNF levels for its treatment." (PMID 40123457, 2025). "For example, it has been observed that in two different mouse models of Huntington’s disease (HD) increased levels of ARMS caused a deficit in the regulated secretion of BDNF." (PMID 37238659, 2023). "To further understand the cause behind the BDNF deficiency in Q140, we have attempted to establish a physiologically relevant study of BDNF transport along the axon and dendrite in a model of Huntington’s disease." (PMID 36829435, 2023). "Changes in BDNF levels and signaling pathways have been identified in several neurodegenerative diseases, including Alzheimer’s disease, Parkinson’s disease, and Huntington’s disease, and have been linked with the symptoms and course of these diseases." (PMID 35743271, 2022). "Reductions in BDNF promoter II and BDNF promoter IV transcriptions have been linked to Huntington’s disease." (PMID 35418836, 2022). "Reports state that decreased levels of BDNF are associated with numerous neurodegenerative disorders such as PD, AD, multiple sclerosis, and Huntington’s disease." (PMID 31906559, 2020). "The stimulation of Y2 receptors by NPY has been shown to increase BDNF level associated with improvement of motor function in a mouse model of Huntington disease." (PMID 31281833, 2019). "Accordingly, BDNF signaling dysfunctions are associated with many neurological and neurodegenerative conditions including Alzheimer’s and Huntington’s disease." (PMID 31017891, 2019). "In Huntington’s disease, an autosomal dominant neurodegenerative disorder, disturbed anterograde axonal transport of BDNF to the striatum causes reduced cortical supply of BDNF which is thought to be responsible for striatal degeneration." (PMID 28280960, 2017). "Impairment of the BDNF-TrkB pathway is suspected to underlie the early dysfunction and prominent degeneration of striatal neurons in Huntington disease (HD)." (PMID 27013968, 2016). "BDNF is a secretory protein with neuroprotective effects which has been shown to be associated with neurodegenerative diseases, including AD, PD and Huntington’s disease." (PMID 27973581, 2016). "Loss of SORLA expression results in impaired neuritic transport of TrkB and in blunted response to BDNF in primary neurons; and it aggravates neuromotoric deficits caused by low BDNF activity in a mouse model of Huntington’s disease." (PMID 23977241, 2013). "Changes in cortical Bdnf expression levels, and/or impairment in brain-derived neurotrophic factor anterograde transport induced by mutant huntingtin (mHdh) are believed to cause striatopallidal neuron vulnerability in early-stage Huntington’s disease." (PMID 23774276, 2013). "The same study found changes in the phosphorylation status of huntingtin (HTT), which acts as a transcription factor and a regulator of BDNF vesicle transport in physiological conditions, and when mutated, is responsible for Huntington’s disease." (PMID 24260418, 2013). "In neurons, BDNF signaling increases Sorl1 transcription 10-fold whereas absence of BDNF activity in mouse models with genetic (Bdnf −/−) or disease-related loss of BDNF in the brain (Huntington’s disease, HD) results in impaired SORLA expression and activity." (PMID 23977241, 2013). "Loss of striatal, cortically-derived BDNF and aberrant histone regulation are two major factors leading to transcriptional dysregulation in Huntington’s disease (HD)." (PMID 24204683, 2013).
Huntington disease (continued). "In a similar manner, in Huntington’s disease, BDNF transport from cortical to striatal neurons is deficient, contributing to selective loss of striatal neurons and voluntary muscle movements in patients with the disease." (PMID 23210531, 2012). "In particular, low brain BDNF levels have been described in various neurodegenerative disorders, most notably, Huntington's Disease (HD), a progressive neurodegenerative disorder caused by a CAG trinucleotide expansion in the gene that encodes huntingtin." (PMID 21857974, 2011). "Studies have implicated reduced levels of brain-derived neurotrophic factor (BDNF) in the pathogenesis of Huntington's disease." (PMID 20507609, 2010). "A promising area of research, as regards adenosine/BDNF cross talk, is Huntington’s disease, which has been associated with low BDNF levels in the cortical-striatal pathway, most probably due to a loss of function of mutated huntingtin." (PMID 20190960, 2009). "Depletion of BDNF has been linked to impairment and death of striatal neurons, leading to the manifestation of motor, cognitive, and behavioral dysfunctions characteristic of Huntington's disease." (PMID 40123457, 2025). "LM22A-4 penetrates the blood–brain barrier reasonably well and has been shown to ameliorate symptoms of other neurological disorders associated with BDNF dysfunction including Rett syndrome, Huntington’s disease, Dravet syndrome, and refractory neonatal seizures." (PMID 37956053, 2023). "The evidence discussed in this article indicates that deficiency in BDNF and TrkB signaling may play a role in the pathophysiology of Alzheimer’s disease, Parkinson’s disease, and Huntington’s disease." (PMID 35743271, 2022). "In addition, changes in BDNF levels and activities have been associated with a variety of neurodegenerative diseases, including Alzheimer’s disease, Parkinson’s disease, Huntington’s disease, and ALS." (PMID 35743271, 2022). "However, BDNF transcription mediated by huntingtin, a protein mutated in Huntington’s disease, was reportedly reduced in Huntington’s disease models." (PMID 30356026, 2018). "BDNF deficiency has been implicated in the pathogenesis of Huntington's disease (HD)." (PMID 26852117, 2016). "Deficiency in BDNF signaling has been linked with an increasing number of conditions that cause brain dysfunction, and the connection between BDNF loss in the striatum and Huntington’s disease (HD) pathology has been extensively investigated." (PMID 25221473, 2014). "Moreover, reduction of BDNF delivery to the striatum has been implicated in the pathophysiology of Huntington's disease." (PMID 19390590, 2009). "Their study clearly proved that a shortage of BDNF supply from cortical to striatal neurons caused by the diminished transport of BDNF as well as the aggregation of mutant htt is a cause of striatal neuronal loss, a common pathological feature of Huntington’s disease." (PMID 29099059, 2017). "Changes in the BDNF/proBDNF ratio have been measured in the peripheral blood and cerebrospinal fluid of both animal models and human patients with Alzheimer’s, Parkinson’s, and Huntington’s disease." (PMID 40430064, 2025). "Decreased levels of BDNF in plasma have been reported in Huntington’s disease (HD) and Gaucher disease (GD)." (PMID 40508163, 2025). "Applications of CRISPR-mediated induction of BDNF have been found to successfully restore corticostriatal connectivity in models of Huntington’s disease, and there is even evidence that they result in decreased neuronal loss and increased life-span." (PMID 40362507, 2025). "BDNF and proBDNF play a critical role in regulating neuronal apoptotic mechanisms in neurodegenerative disorders, including Alzheimer’s (AD), Parkinson’s (PD), and Huntington’s diseases (HD)." (PMID 40430064, 2025). "This review highlights the current update on the neurobiology of BDNF in the pathogenesis of Huntington's disease." (PMID 40123457, 2025).